MGMT (O-6-methylguanine-DNA methyltransferase)
Diseases named in the same sentence as MGMT in open-access papers (continued):
Sharing a sentence is not in itself a finding about the gene and the disease.
glioma (continued). "Moreover, promoter methylation can silence MGMT expression in gliomas." (PMID 27057637, 2016). "Thus, MGMT is an important predictive marker for high-grade gliomas." (PMID 27158275, 2016). "The current study shows that the HIV-derived protein Vpr induces apoptosis in glioma cells, acts independently from MGMT expression status, is tolerated well when given intravenously, delays intracranial tumor growth and prolongs survival in a relevant pre-clinical model of high-grade glioma." (PMID 27275537, 2016). "Comparative analysis evidenced the miR-181d expression in glioma tissues as inversely correlated with a favourable prognosis in these patients and that the favourable effect of miR-181d is, at least partially, related to its effect in downmodulating MGMT mRNA expression." (PMID 26035292, 2015). "Molecular characteristics, including methylation of O6-methylguanine-DNA methyltransferase (MGMT) promoter, isocitrate dehydrogenase 1 or 2 (IDH1/2) gene mutations, or 1p/19q chromosomal loci deletion, are currently used to genetically classify glioma patients." (PMID 25695077, 2015). "Therefore, it warrants further studies to validate our findings in MGMT-positive glioma cell lines." (PMID 24555568, 2014). "Thus, both genetic and epigenetic alterations contribute to MGMT silencing in high-grade gliomas." (PMID 23505468, 2013). "In addition, it was also suggested that integrin inhibition coupled with the methylation of a DNA repair enzyme O-6-methylguanine-DNA methyltransferase (MGMT) gene promoter could be involved in the increased TMZ sensitivity of gliomas." (PMID 23704872, 2013). "Given the high frequency of DNA methylation changes, these events may become ideal biomarkers for early molecular diagnostics, such as MGMT, which has been observed to be hypermethylated in low-grade gliomas (grade II) further evolving to gliomas grade III and GBM." (PMID 22778947, 2012). "This study involved longitudinal analysis samples of primary and recurrent gliomas to determine whether the progression of low- and high-grade gliomas is associated with the promoter methylation of the DNMT1, MGMT and EGFR genes by PCR-based restriction enzyme assay." (PMID 22264301, 2012). "Therefore, we speculated that an even greater therapeutic efficacy of pG8-FasL/FADD and TMZ could be achieved in human glioma cells with generally low MGMT activity." (PMID 20942909, 2010). "This downregulation of MGMT expression led to an increase in the cytotoxic effects of TMZ, sensitizing previously resistant glioma cells and patient-derived gliomaspheres to standard chemotherapy." (PMID 41817895, 2026). "For example, MGMT promoter methylation predicts improved responses to temozolomide, while the G-CIMP phenotype, most commonly observed in IDH-mutant gliomas, defines a distinct epigenetic and prognostic subgroup." (PMID 41596524, 2026). "Additionally, IDH mutations often co‐occur with glioma‐associated genetic alterations including BRAF, TERT promoter, 1p/19q co‐deletion, and MGMT promoter methylation, which may also result in shifts of metabolic pathways and the spatial heterogeneity of H2O2/GSH ratio." (PMID 40171868, 2025). "We performed immunofluorescence (IF) staining on a glioma tissue microarray (TMA) comprising 92 glioma samples and adjacent non-tumor tissues to assess the correlation between USP7 and MGMT expression." (PMID 40835840, 2025). "As additionally highlighted by Jiang, earlier studies have used a mixed cohort of gliomas including WHO Grades II–IV or III–IV, and investigated either MGMT and IDH status alone or together." (PMID 40560010, 2025).
glioma (continued). "On the unified TCGA-GBM/LGG and Erasmus Glioma Database (EGD) test cohort, MGMT-Net achieved AUC scores of 0.94 (IDH), 0.91 (1p/19q), and 0.90 (TERT), outperforming the best baseline model, which reached 0.92, 0.89, and 0.86, respectively." (PMID 41007223, 2025). "Although DKI can predict glioma grades (HGG or LGG) stably, the utility of DKI for predicting glioma genotypes, like IDH, ATRX, MGMT genetic statuses, remains controversial." (PMID 40352771, 2025). "Together, these findings underscore that MMR deficiency is a frequent, treatment-emergent mechanism of resistance to TMZ in MGMT-methylated and IDH-mutant gliomas." (PMID 41169667, 2025). "This hierarchical relationship positions G-CIMP as a global epigenetic driver and MGMT methylation as a therapeutically consequential downstream effector, collectively contributing to the favorable prognosis of IDH-mutant gliomas." (PMID 40426960, 2025). "Moreover, the inverse correlation between ESURATAG-GS and MGMT promoter methylation in gliomas, a key determinant of therapeutic response, suggests that tumors with high ER stress burden may be more resistant to standard alkylating chemotherapy, reinforcing the therapeutic relevance of this pathway." (PMID 40718795, 2025). "Univariate and multivariate Cox regression analyses were performed to evaluate the impact of Radiotherapy, Chemotherapy, WHO grade, IDH status, MGMT methylation status, 1p19q codeletion status, age, gender, and CD9 expression on glioma prognosis." (PMID 40406701, 2025). "The ATRX, OLIG2, MGMT, and IDH2 networks highlight key molecular interactions that contribute to glioma development, progression, and therapeutic resistance." (PMID 40282990, 2025). "For example, MGMT methylation status influences temozolomide response, and IDH1 inhibitors such as ivosidenib are being investigated in gliomas." (PMID 41311621, 2025). "We focus on KL-50, a next-generation imidazotetrazine designed to induce MGMT-dependent, MMR-independent DNA crosslinks, representing a rational approach to selectively target MGMT-silenced, treatment-refractory gliomas." (PMID 41169667, 2025). "This was particularly evident among low-grade gliomas, where only 32% of low-grade IDH1/2-mutant gliomas were assessed for MGMT-methylation status compared to 52% of high-grade and 82% of grade 4 IDH1/2-mutant gliomas." (PMID 39164213, 2025). "Both of these cell lines are grade 4 gliomas; however, the U-87 MG cell line has an MGMT methylated promoter and is defined as TMZ sensitive, whereas the U-138 MG cell line has an MGMT unmethylated promoter and is regarded as TMZ resistant." (PMID 39859375, 2025). "In glioma, resistance to TMZ and therapeutic failure are mainly determined by overexpression of O6-methylguanine-DNA methyltransferase (MGMT), an enzyme that plays a key role in reverting the alkylation process done by TMZ." (PMID 41050069, 2025). "We categorized the patients from the TCGA-glioma cohort based on clinical features such as age, gender, grade, IDH status, 1p/19q co-deletion, and MGMT promoter status." (PMID 40661083, 2025). "In this phase I clinical trial, we examined the safety and tolerability of adding the oral CA inhibitor ACZ to standard adjuvant TMZ in patients with MGMT promoter-methylated GBM and high-grade glioma." (PMID 38420615, 2024). "Data, including transcriptomic and clinical information, as well as information on MGMT promoter methylation status in primary GBM, were obtained from The Cancer Genome Atlas (TCGA) (n=121) and Chinese Glioma Genome Atlas (CGGA) (n=83) datasets." (PMID 38288307, 2024). "The O6-methylguanine DNA methyltransferase (MGMT) promotor methylation decreases the gene expression and improves glioma response to radiotherapy and alkylating agents." (PMID 38893257, 2024).
glioma (continued). "They loaded O6-benzylguanine (an inhibitor for MGMT) and temozolomide (TMZ, a first-line agent for treatment) for a therapy targeting TMZ-resistant gliomas." (PMID 39057463, 2024). "A randomized trial in patients with recurrent high-grade glioma demonstrated the independent prognostic significance of IDH1/2 and MGMT methylation status for prolonged OS." (PMID 39049072, 2024). "Most importantly, the outcome of patients with gliomas was not significantly improved after treatment with O6‐BG in those clinical trials, suggesting that the activation of the MGMT‐associated signaling pathway could compensate for the disruption of MGMT by O6‐BG." (PMID 39041891, 2024). "Levetiracetam (LEV), a newer antiepileptic drug, regulates HDAC levels to silence MGMT, thus enhancing TMZ’s effectiveness against glioma stem cells (GCSs)." (PMID 38927583, 2024). "Via lentiviral-mediated delivery into LN18 glioma cells, we employed deactivated Cas9-CRISPR technology to target the MGMT promoter and enhancer regions for methylation, as mediated by the catalytic domain of the methylation enzyme DNMT3A." (PMID 38224404, 2024). "Since both methylation of the MGMT promoter and MMR function can be disrupted in glioma cells, the therapeutic effect of temozolomide is often limited." (PMID 38673835, 2024). "Other independent prognostic variables included older age (> 45 years), high-grade glioma, wild-type IDH, 1p/19q co-deletion, and unmethylated MGMT promoter status." (PMID 39333557, 2024). "While our study cohorts were stratified by IDH status, we performed multivariate analysis to attempt to control for additional potential confounders including age, MGMT methylation, TMZ treatment, and chromosomal abnormalities commonly found in glioma." (PMID 39553337, 2024). "Furthermore, independence analysis and subgroup analysis indicated that OS-EMT-ICI genes-associated risk model could independently predict glioma prognosis, irrespective of age, gender, and MGMT methylation status." (PMID 38511063, 2024). "The drug-loaded hydrogels reduced MGMT expression in vivo, rendering TMZ-resistant glioma cells more responsive to TMZ treatment." (PMID 39057463, 2024). "The common occurrence of extensive necrotic areas in high-grade gliomas with IDH-wildtype and MGMT-unmethylated often limits tumor expansion." (PMID 38167551, 2024). "Gene + OncoGlioma glioma gene test covers 1,021 genes and combines NGS with hybridization enrichment and pyrosequencing to analyze MGMT methylation status (Gene+|OncoGlioma, 2023)." (PMID 37908227, 2023). "A HH/Gli1 inhibitor (GANT61) was found to sensitize U87MG and U251MG glioma cells to TMZ treatment by enhancing the DNA damage effect, suppressing MGMT expression and the Notch1 pathway." (PMID 36675073, 2023). "High CD44 expression correlates with unmethylated MGMT promoter, suggesting that CD44+ glioma cells confer TMZ resistance." (PMID 36989359, 2023). "Primary genetic markers such as IDH mutations, CDKN2A deletions, 1p/19q‐codeletions, H3F3A alterations, MGMT promoter methylation status and EGFR amplification are used in the glioma classification system." (PMID 36999945, 2023). "In this study, we employed a pyrosequencing-based analysis of CpG’s 1–8 in the promoter region of the MGMT gene using bisulfite converted DNA from FFPE tumour samples, adopting a protocol commonly used in routine clinical practice for glioma samples." (PMID 36198483, 2023).
glioma (continued). "O6-methylguanine-DNA methyltransferase (MGMT) methylation, 1p/19q co-deletion, IDH, and epidermal growth factor receptor have been widely used as glioma biomarkers." (PMID 36819921, 2023). "In grade 4 gliomas, methylation status of MGMT (O-6-Methylguanine-DNA Methyltransferase) gene promoter has been identified as a robust and independent predictive factor for the response to temozolomide, the first-line chemotherapy for grade 4 gliomas." (PMID 37580817, 2023). "In glioma, we investigated that LAIR‐1 overexpression was interrelated with clinicopathologic features such as grade, IDH status, 1p/19q non‐co‐deletion, and MGMT, suggesting that LAIR‐1 overexpression participates a role in the malignant behavior of glioma." (PMID 35702880, 2023). "Our study has highlighted the intricate relationship between molecular biomarkers such as RYK expression and MGMT methylation and IDH mutant statuses, as well as their impact on patient survival outcomes in different types of gliomas." (PMID 37242509, 2023). "The correlation of the MGMT-promoter methylation status with response to TEM has been proved in brain tumors, and its assessment is standard in gliomas." (PMID 36826067, 2023). "We analyzed the survival rate of glioma patients in the CGGA database and found that RAD51AP1 is a better prognostic factor in MGMT-methylated patients." (PMID 37283490, 2023). "Regarding MGMT methylation status, ISG20 was overexpressed in glioma tissues with unmethylated MGMT (P < 0.001)." (PMID 37380984, 2023). "The second is O6-methylguanine-DNA methyltransferase promoter methylation (MGMT-m), a favorable independent prognostic biomarker, which can predict glioma patients’ response to temozolomide." (PMID 36471242, 2022). "The results in TCGA and the three CGGA datasets all suggested that gliomas in cluster 1 had a higher pathological grade, and cluster 2 had lower levels of IDH WT and MGMT promoter unmethylation." (PMID 36159780, 2022). "Previous studies indicated that promoter methylation of O-6-methylguanine-DNA methyltransferase (MGMT), a key member involved in the DNA repair, would increase the sensitivity of glioma cells or tissues to TMZ." (PMID 36118887, 2022). "Of all analyzed MGMT methylated gliomas, 19% showed EGFR amplification, and 22% of MGMT unmethylated gliomas showed an EGFR amplification." (PMID 35453544, 2022). "Next, we drew KM curves of the risk score signature stratified by IDH-mutant status, 1p/19q codeletion, MGMT promoter methylation, age, and WHO grade in the glioma patients of the training and validation cohorts." (PMID 36035133, 2022). "Patients with MGMT promoter methylation, which is more common in IDH-mt glioma, exhibited good sensitivity to alkylating agents targeting DNA damage." (PMID 35287567, 2022). "TMZ16e was concluded to effectively increase the consumption of MGMT, thus reversing TMZ resistance and improving glioma treatment efficacy." (PMID 36059989, 2022). "Previous studies on the biomarkers of glioma mainly focused on epidermal growth factor receptor (EFGR) amplification, chromosome 1p/19q deletion, O6-methylguanine DNA methyltransferase (MGMT) promoter methylation, and isocitrate dehydrogenase (IDH) mutations." (PMID 36605437, 2022). "Analyses of GBM transcript expression databases revealed correlations of elevated CD146 levels with higher glioma grades, IDH-wildtype and unmethylated MGMT phenotypes, poor response to chemo-radiotherapy and worse overall survival." (PMID 35790583, 2022). "This will surely impair the function of repairing DNA for MGMT, which is beneficial to the therapeutic effect of temozolomide (TMZ) for glioma patients." (PMID 36338770, 2022). "ROCK2 expression was associated with poor overall survival of MGMTlow (MGMT−) recurrent gliomas with TMZ therapy (n = 100), compared with MGMThigh (MGMT+) subset." (PMID 35145081, 2022). "It is reported that there was a strong positive correlation between MGMT activity and TMZ tolerance of tumors in gliomas." (PMID 36248966, 2022).
glioma (continued). "DWI metrics, including nADC and omADC from the solid part of the glioma, have a potential ability to predict tumor grade and IDH-mut, but have limited use in the prediction of TERT-mut and MGMT-m." (PMID 36471242, 2022). "As shown here, the glioma in vivo model used in this study is IDH-wt, which is expected to respond to the TMZ treatment since the MGMT promoter is highly methylated." (PMID 36230732, 2022). "GBMs appropriate for SMR are commonly located on the prefrontal lobe, where a high percentage of GBMs was glioma-CpG island methylator phenotype (G-CIMP) subtype and MGMT promoter methylated." (PMID 35185770, 2022). "The MGMT promoter methylation is present in approximately 80% of WHO grade 2 and 35–45% of WHO grade 3 and 4 gliomas." (PMID 35563629, 2022). "Specifically, four prognostic groups for imaging research pertaining to gliomas can be recognized: IDH status, 1p/19q status, MGMT status, and H3G34 status." (PMID 36289752, 2022). "In contrast, weak expression of MGMT indicates MGMT promoter is highly methylated, and weak expression of HIF-1α means low hypoxia in the GSC gliomas." (PMID 36591483, 2022). "Our results showed that constructed multiparametric model from MRI radiomics features can identify phenotype status of IDH, MGMT and TERT in preoperative MRI scans of patients with glioma." (PMID 35931979, 2022). "For WHO II-IV gliomas, we found that ADC values had less accuracy and reliability in discriminating MGMT and TERT status, which limited the use of DWI metrics in predicting these two genotypes." (PMID 36471242, 2022). "High grade-gliomas (HGG, WHO grades 3 and 4) were more likely to have MGMT promoter methylation, which was available in six patients: low in one patient, medium in four patients, and high in one patient." (PMID 34827431, 2021). "In another example, FOXD2-AS1 reduced methylation and increased activity of O6-methylguanine-DNA methyltransferase (MGMT), which is a treatment response predictor in glioma." (PMID 34322395, 2021). "Our study revealed that TMZ‐resistant glioma cells were characterized by high expression levels of RIP2 and MGMT, as well as enhanced NF‐κB activity." (PMID 33460245, 2021). "Cox regression analysis showed that in grade IV glioma, preoperative PNI level, extent of resection, and MGMT methylation status were significantly correlated with OS." (PMID 35096561, 2021). "MGMT promoter methylation is a key mechanism of MGMT gene silencing and predicts a favorable TMZ chemotherapy outcome in glioma patients." (PMID 34739394, 2021). "Honokiol specifically inhibits PI3K/mTOR signaling activation in gliomas, promotes the elimination of GSCs, and reverses TMZ resistance using GBM8401 SP cells, which appear to have higher expression of MGMT and to be more resistant to TMZ." (PMID 33762015, 2021). "We also correlated MGMT promoter methylation data from our GSC and glioma cell lines with ATIP1 expression." (PMID 33809019, 2021). "Furthermore, siPOOL mediated knockdown of ERK5 also sensitised resistant LN18 cells to TMZ as well as the more TMZ sensitive U87 and U-251 cells, demonstrating that targeting of ERK5 could potentially potentiate TMZ cytotoxicity in both MGMT+ and MGMT− glioma cell backgrounds." (PMID 33668183, 2021). "After adjusting for the five clinicopathological factors (age, grade, IDH status, 1p/19q status and O6-methylguanine-DNA methyltransferase (MGMT) status), ANXA2 expression remained an independent prognostic factor for glioma patients." (PMID 34675316, 2021). "In glioma, a number of oncogenic landmarks have been identified previously, such as somatic alternations on IDH, O-6-methylguanine-DNA methyltransferase (MGMT) promoter, TERT promoter, and chromosome 1p/19q co-del." (PMID 34540693, 2021).